SNORD116-19 (small nucleolar RNA, C/D box 116-19)
Synonyms: HBII-85-19
Gene: Small nucleolar RNA gene on chromosome 15 (25,086,527 to 25,086,618, forward strand). Ensembl gene ENSG00000207460.
Gene Ontology:
Biological process: RNA processing
Cellular component: nucleolus
Homologues: Orthologues: macaque SNORD116 (100% identical), chimpanzee SNORD116 (95% identical), guinea pig SNORD116 (90% identical), guinea pig SNORD116 (86% identical). Paralogues in human: SNORD116-17 (100% identical), SNORD116-14 (99% identical), SNORD116-15 (99% identical), SNORD116-18 (99% identical), SNORD116-20 (99% identical), SNORD116-21 (99% identical), SNORD116-22 (99% identical), SNORD116-16 (97% identical), SNORD116-12 (93% identical), SNORD116-23 (93% identical), SNORD116-24 (93% identical), SNORD116-2 (89% identical), and 20 more.